SET (SET nuclear proto-oncogene)
Diseases named in the same sentence as SET in open-access papers (continued):
Sharing a sentence is not in itself a finding about the gene and the disease.
cancer (continued). "Other genes with known roles in cancer included Smoothened, a G-protein coupled receptor in the hedgehog pathway; the transcriptional activator Eya2; the histone-binding oncoprotein SET; and the mTOR inhibitor Depdc6." (PMID 21559491, 2011). "Most of the SET molecule is included in the SET-NUP214 fusion protein, and these observations suggest that SET (and possibly also SET-NUP214) associated chemoresistance can be seen in certain cancer cells and include resistance to various anticancer agents." (PMID 41002427, 2025). "To corroborate SET-ZBTB11 complex-mediated modulation of cancer cell behaviors in vivo, we employed H1299-Luc2-tdT-2 reporter cells with stable knockdown of SET or ZBTB11 and monitored distal metastasis of the indicated cancer cells through a subcutaneous tumor xenograft mouse model." (PMID 38355937, 2024). "Increased SET protein plays a pivotal role in the progression of various cancer types." (PMID 38141761, 2024). "Since knockdown of ZBTB11 displayed a more robust effect on cancer cell migration and invasion than SET depletion, we speculated that ZBTB11 likely maintains additional ways to modulate metastasis independent of SET-ZBTB11 complex formation." (PMID 38355937, 2024). "Furthermore, it is a tumor‐promoting factor, and increased SET expression has been reported in various types of cancers." (PMID 37489294, 2023). "As for OV, Qiao and colleague reported that SETBP1 could maintain the Cancer Stem Cell (CSC)-like phenotype of tumor cells via the SET/PP2A axis." (PMID 37730669, 2023). "High SET expression positively correlates with a poor cancer prognosis." (PMID 37489294, 2023). "Given the role of SET in PP2A inactivation and downstream pathways involved in oncogenic signaling and converging on hyperphosphorylation of tau, SET could represent a valuable target for treatment of cancer and AD." (PMID 36345878, 2022). "Therefore, our study reveals the key role of SET in controlling the intratumoral localization of TAMs and highlights the clinical importance of SET as a target for cancer immunotherapy." (PMID 36224346, 2022). "To test this hypothesis, we first determined whether overexpression of SET or/and CIP2A co-occurred with mutations of ERK-activating oncogenes in human cancers." (PMID 36463234, 2022). "Thus, SET/CIP2A-mediated PP2A suppression in cancer is particularly important for the induction of NELF-A phosphorylation." (PMID 36463234, 2022). "SET overexpression, reducing PP2A activity, has been reported and associated with a poor prognosis in chronic lymphocytic leukemia of B, CML, AML cells, and other types of cancer." (PMID 34058077, 2021). "Likewise, increased SET expression has been associated with resistance to TKI's, cisplatin, paclitaxel, oxaliplatin, and 5-fluoro-uracil in diverse cancer types." (PMID 31214504, 2019). "In this context, we will provide the latest and comprehensive overview of SET in cancer including characterization of SET and its homologs, its functional roles and underlying mechanisms and transcriptional and post‐translational regulation as well as its potential as a therapeutic target." (PMID 29749127, 2018). "Several SET antagonists have been developed and extensively evaluated for cancer therapy." (PMID 29749127, 2018).
cancer (continued). "Therefore, the SET protein is regarded as a potential target for cancer therapy and several inhibitors are being developed for clinical use." (PMID 29749127, 2018). "SET overexpression increases significantly as cancer progression occurs." (PMID 29749127, 2018). "Since decreased phosphatase function and increased kinase activity is a hallmark of cancer progression, we tested whether activating PP2A through SET antagonism, in combination with tyrosine kinase inhibitors, would reduce survival of T-ALL cells." (PMID 27705940, 2016). "Interestingly, we found that the pro-apoptotic effects of paclitaxel were significantly diminished in cancer cells with SET overexpression." (PMID 26575017, 2016). "Revelation of ZFX-mediated transactivation of SET provides one mechanism by which ZFX may be implicated in multiple cell functions, e.g., those related to cancer development." (PMID 27775603, 2016). "In addition to mutations on the regulatory subunits, the phosphatase/tumor suppressing activity of PP2A is also inhibited in several cancer types due to overexpression or modification of the endogenous PP2A inhibitors such as SET/I2PP2A." (PMID 25642418, 2014). "To define the clinical relevance of I2PP2A/SET-C18-ceramide in cancer pathogenesis, we measured I2PP2A/SET and C18-ceramide in tumour versus pathologically non-cancerous adjacent lung tissues obtained from 10 patients with NSCLC using Western blotting and immunohistochemistry (IHC)." (PMID 23180565, 2013). "Indeed, although overexpression of both ZBTB11 and SET displayed a promotive effect on cancer cell migration and invasion, only full-length SET, but not acidic domain-truncated SET that failed to bind with ZBTB11, enhanced ZBTB11-dependent metastatic regulation." (PMID 38355937, 2024). "Thus, SET has been shown to be overexpressed in a multitude of cancers." (PMID 35814385, 2022). "Thus, overexpression of SET protein leads to progression of human cancer." (PMID 30341686, 2018). "In addition, TSA diminished both SET protein levels and SET capability to bind to gene promoter, suggesting that administration of epigenetic modifier agents could be efficient to reverse SET phenotype in cancer." (PMID 28460463, 2017). "Therefore, high SETBP1 levels may also confer a poor outcome in cancer through increased activity of SET and subsequent inhibition of PP2A." (PMID 27705940, 2016). "Our finding that SET is frequently overexpressed in NSCLC cancers is novel and suggests that deregulation of SET as a possible contributing mechanism to inhibit PP2A, and overexpression of PP2A inhibitors may play an important role in the development of human NSCLC." (PMID 25945834, 2015). "However, mechanisms involved in the regulation of PP2A-I2PP2A/SET interaction for controlling PP2A-dependent tumour suppression in human cancer cells have been largely unknown." (PMID 23180565, 2013). "Thus, it is intuitive that genetic (mutations in the gene encoding a specific PP2A subunits) or functional (e.g. PP2AcY307 phosphorylation, SET overexpression) inactivation of PP2A may represent a step required for cancer development and/or progression." (PMID 16953242, 2006). "Noteworthy, SET proteins present promising drug targets and HMT inhibitors are currently in clinical trials to test their use in cancer therapy." (PMID 39445823, 2024). "The decrease in PP2A activity has been observed in various cancers, and the increase in endogenous PP2A inhibitory proteins such as SE translocation (SET, also called I2PP2A and TAF-1) contributes to this." (PMID 38141761, 2024). "Since SET and CIP2A are commonly overexpressed in human cancers, we think that cancer preventive agents can act by reducing the overexpression of SET and CIP2A." (PMID 37097392, 2023). "The binding complex of SET and CIP2A with PP2A remains to be further investigated in cancer research." (PMID 37097392, 2023).
cancer (continued). "Screening 107 overall survival-related cancer genes and 402 interacting gene pairs, 6 genes: CRLF2, HSP90AA1, MAP2K1, PAFAH1B2, MYCL and SET genes, were identified and a transcriptional score was obtained." (PMID 37897503, 2023). "Okadaic acid class of tumor promoters are transformed into endogenous protein inhibitors of PP2A, SET, and CIP2A in human cancers." (PMID 37097392, 2023). "In about 10% of human cancers, PP2A is inhibited by genomic mutations, but the most prevalent mechanism for PP2A inhibition in cancer is overexpression of one of the numerous oncogenic PP2A inhibitor proteins such as CIP2A, PME-1, or SET." (PMID 36858798, 2023). "This suggests that overexpression of SET and CIP2A induces strong inhibition of PP2A activity in human cancer cells, as okadaic acid does." (PMID 37097392, 2023). "Further, endogenous cellular inhibitors such as cancerous inhibitor of PP2A (CIP2A) and inhibitor 2 of PP2A (I2PP2A; commonly known as SET) restrains PP2A activity and are often found to be overexpressed in cancer." (PMID 37234102, 2023). "Given the importance of PP2A in reversing oncogenic phosphorylation and since SET is a crucial endogenous inhibitor of PP2A, the expression of SET in cancers and its pharmacological reactivation have been the focus of intense investigations." (PMID 35814385, 2022). "By interfering with the PP2A-mediated dephosphorylation, SET activates oncogenic signaling such as AKT, ERK, c-MYC and GSK3-β to promote the survival and proliferation of cancer cells." (PMID 36345878, 2022). "We confirmed that enhanced expression of SET or CIP2A is sufficient to promote strong NELF-A phosphorylation and IEG expression in H1299 cancer cells harboring NRASQ61K." (PMID 36463234, 2022). "Functional mechanisms including post-translational modifications of catalytic and regulatory PP2A subunits and aberrant expression of PP2A endogenous inhibitors SET, SETBP1 and CIP2A represent novel emerging mechanisms for PP2A regulation in cancer." (PMID 36345878, 2022). "Recently, reactivation of PP2A activity using small molecules that either antagonise its inhibitors (SET and CIP2A), or directly activate PP2A, has attracted attention as a new strategy for cancer therapy." (PMID 34244560, 2021). "The phosphorylation of the PP2A catalytic subunit in its tyrosine 307, as well as the overexpression of endogenous inhibitors such as SET, have been reported as major contributing alterations to inhibit PP2A in human cancer." (PMID 33809005, 2021). "Functional studies indicated that miR-1915-3p suppressed cancer migration, invasion and EMT of NSCLC via directly targeting oncogene SET." (PMID 34774019, 2021). "Therefore, better understanding of the defects in relation to SET regulated proteins could potentially lead to the development of novel therapeutic remedies such as targeting acetylation/deacetylation to circumvent the dysregulation by SET in cancer and mental illness." (PMID 30858352, 2019). "SE translocation (SET), an inhibitor of protein phosphatase 2A (PP2A), plays important roles in mitosis and possesses oncogenic activity in several types of cancer." (PMID 31097686, 2019). "However, the regulation of SET in mitosis and its possible role in cancer have remained unknown." (PMID 31097686, 2019). "Inhibition of miR-502-3p upregulates SET which activates AKT signaling, resulting in cancer progression." (PMID 31752906, 2019). "In summary, the okadaic acid class of tumor promoters are transformed into SET and CIP2A, which induce tumor promotion, progression and inflammation in various human cancer cells, which are the results of some life-style related diseases." (PMID 30341686, 2018). "Tumor promotion among rodents with the okadaic acid class compounds is revived in human cancer progression by the endogenous protein inhibitors of PP2A, SET and CIP2A." (PMID 30341686, 2018).
cancer (continued). "Endogenous protein inhibitors of PP2A, SET and CIP2A have led to a new strategy for treatment of cancer, based on evidence that SET and CIP2A knockdowns with siRNA or RNAi and SET antagonists, such as OP449 and FTY720, significantly reduced tumor growth." (PMID 30341686, 2018). "This will help us to understand the molecular mechanism of SET and CIP2A overexpression in cancer cells." (PMID 30341686, 2018). "Increased accumulation of the SET oncoprotein in these cancer cells accounts for decreased PP2A activity, and overexpression of SET promotes cell proliferation, survival, drug resistance, invasion and metastasis." (PMID 25945834, 2015). "Similar results from recently studies of treatment with another SET inhibitor OP449 showed activation of PP2A, as well as suppressed the tumor growth of cancer." (PMID 25945834, 2015). "Moreover, we successfully detected the interaction between endogenous SET and ZBTB11 in H1299 cells, indicating that the SET-ZBTB11 protein complex can form under physiological conditions in cancer cells." (PMID 38355937, 2024). "Since overexpression of SET and CIP2A induces cancer progression, and knockdown of SET and CIP2A inhibits tumor growth, the effects of anticancer drugs might be different in between cancer cells with SET and CIP2A and those with their knockdown." (PMID 37097392, 2023). "How overexpression of SET and CIP2A proteins is induced in cancer cells remains to be investigated." (PMID 37097392, 2023). "Thus, the aberrant PP2A inhibition by SET/CIP2A and ERK hyperactivation by oncogenes coexist in many clinical cancer cases." (PMID 36463234, 2022). "Although no Metnase SET inhibitors are available, specific SET inhibitors are being developed to treat cancer." (PMID 35155245, 2022). "In addition to FTY720, novel specific SET-antagonist peptides such as OP499 and COG112 are currently under development for cancer therapy." (PMID 36345878, 2022). "Since we used a pan-SET antibody in this CTC study, further investigations using specific antibodies for SET-α and SET-β will provide more insights into the significance of SET isomers in cancer progression." (PMID 34244560, 2021). "In addition to SET, cancerous inhibitor of PP2A (CIP2A), another well-known cellular inhibitor of PP2A, is often overexpressed in various cancer tissues." (PMID 34244560, 2021). "Similarly, higher SET and CIP2A levels in human CRC cancers are positively correlated with CD8+ cytotoxic T infiltration but negatively correlated with Foxp3+ Treg infiltration." (PMID 34911954, 2021). "The cellular PP2A inhibitors oncoprotein I2PP2A (SET) and cancerous inhibitor of PP2A (CIP2A) affect drug resistance and cell survival in many cancers; subsequently, CIP2A downregulation and SET inhibition activate PP2A and restore chemosensitivity to cisplatin as well as reduce tumor burden." (PMID 32927892, 2020). "In addition to CIP2A, SET nuclear proto-oncogene (SET) oncoprotein is another intrinsic inhibitor of PP2A, participating in cancer progression." (PMID 30154367, 2018). "Endogenous protein inhibitors of PP2A, SET and CIP2A, were up-regulated in various human cancers, so it is vital to review the essential mechanisms of tumor promotion by the okadaic acid class compounds, together with cancer progression by SET and CIP2A in humans." (PMID 30341686, 2018). "Furthermore, it has been shown that high levels of SET and CIP2A at diagnosis are biomarkers for cancer progression in leukemia and confer a poor prognosis." (PMID 27705940, 2016). "Furthermore, we showed that the synergistic anti-cancer effects by combining a novel SET antagonist, EMQA, and paclitaxel, and the synergism of this combination was determined by inhibition SET/PP2A/p-Akt signaling." (PMID 26575017, 2016). "Since SET is overexpressed in cancer cells, from a pathologic point of view, we are more interested in factors upregulating SET expression, and the E2F3a-mediated negative effects was not pursued further." (PMID 27775603, 2016).
cancer (continued). "The commonality of PP2A inhibition by SET oncoprotein, which is overexpressed in various tumor tissues compared to non-cancerous tissue counterparts, makes SET a promising target for cancer therapeutics." (PMID 25642418, 2014). "SET and ZBTB11 jointly promoted cancer cell metastasis, but the mechanisms could be diversified." (PMID 38355937, 2024). "In addition to prevention of colorectal adenoma by green tea catechins, it is worthwhile to study whether green tea catechins inhibit overexpression of SET and CIP2A along with PP2A activity in cancer cells, as suitable targets for cancer prevention." (PMID 37097392, 2023). "Moreover, SET antagonists, such as OP449 and FTY720 inhibited proliferation of cancer cells." (PMID 37097392, 2023). "As Ser9 phosphorylation triggers not only SET translocation to the cytosol but it also increases the affinity between SET and PP2A, strategies to target this phosphorylation might provide a novel therapeutic approach for cancer and AD." (PMID 36345878, 2022). "However, when PP2A inhibitor proteins, such as SET and CIP2A, are overexpressed, as is frequently found in human cancers, decreased PP2A activity allows enhanced NELF-A phosphorylation; this causes aberrant upregulation of IEGs and associated downstream growth-promoting genes, and tumor progression." (PMID 36463234, 2022). "Interestingly, our findings demonstrate a key role of SET in cancer progression mediating cell migration, colony-formation and EMT but these observations for SET in CRC have to be also evaluated in other tumor models with SET deregulation." (PMID 30871013, 2019). "It included a number of genes with obvious cancer relevance including CD44, catenin b1 (CTNNB1), vimentin (VIM), cathepsins B and S (CTSB, CTSS), MMP9, XIAP, JunD, numerous proto-oncogenes (REL, YES, SET, FGR, CRK), and HSP90AA1 (which is a chaperone which stabilizes MIF as a client)." (PMID 28957348, 2017). "Analyses of large-scale cancer genomics datasets showed significantly higher expression of SET and CIP2A in various cancers than in their corresponding normal tissues." (PMID 36463234, 2022). "Here, the four peptides (iRGD-IP, RPARPAR-IP, LinTT1-IP, and TT1-IP) that block the PP2A/SET interaction were able to penetrate tumoral hepatocytes isolated from HCC, but crucially, they were not internalized by non-malignant tumors." (PMID 34683924, 2021). "Re-expression of SET-FL, but not SET-ΔAD, which does not bind with ZBTB11, obviously elevated cell migration and invasion, suggesting that the interaction between SET and ZBTB11 is critical for SET/ZBTB11-mediated metastatic regulation of cancer cells." (PMID 38355937, 2024). "In fact, SET was shown to regulate the Ku70/80-mediated non-homologous-end-joining (NHEJ) repair by inhibiting CBP acetylation of Ku7062 and to promote chromatin compaction to negatively regulate repair by homologous recombination in cancer cells." (PMID 34193871, 2021).